GLTPD2 (glycolipid transfer protein domain containing 2)
Tractability: PROTAC: its protein half-life has been measured.
Gene: Protein-coding gene on chromosome 17 (4,788,964 to 4,790,589, forward strand). Ensembl gene ENSG00000182327.
Subcellular location (Human Protein Atlas): Vesicles; Nucleoplasm; Predicted to be secreted
Gene Ontology:
Molecular function: ceramide 1-phosphate binding; lipid transfer activity
Biological process: ceramide transport; intermembrane lipid transfer; negative regulation of interleukin-1 beta production
Cellular component: cytosol; cytoplasm
Genetic constraint (gnomAD): Loss-of-function variants: 14 observed, 12.31 expected, observed/expected ratio (o/e) 1.14, 90% interval 0.75 to 1.73. The synonymous counts are far from expectation, so gnomAD's model fits this gene poorly and the ratio says little. Missense variants: 450 observed, 345.1 expected, observed/expected ratio (o/e) 1.3, 90% interval 1.21 to 1.41. Synonymous variants: 199 observed, 154.83 expected, observed/expected ratio (o/e) 1.29, 90% interval 1.14 to 1.45.
Homologues: Orthologues: chimpanzee GLTPD2 (98% identical), dog GLTPD2 (71% identical), pig GLTPD2 (69% identical), rabbit GLTPD2 (66% identical), rat Gltpd2 (65% identical), mouse Gltpd2 (65% identical), guinea pig GLTPD2 (52% identical), tropical clawed frog gltpd2 (27% identical), zebrafish gltpd2a (26% identical), zebrafish cptp (25% identical), zebrafish gltpd2b (25% identical), Drosophila melanogaster CG30392 (25% identical), and 5 more. Paralogues in human: CPTP (26% identical), PLEKHA8 (19% identical), GLTP (13% identical), CERT1 (12% identical), PLEKHA3 (7% identical).
Diseases named in the same sentence as GLTPD2 in open-access papers:
GLTPD2 is named in the same sentence as 7 diseases in open-access papers, as found by Europe PMC text mining. Sharing a sentence is not in itself a finding about the gene and the disease. The quoted sentences say what the papers report.
angina (1 paper, 2019). "These included novel associations of variants at COL5A1 with cerebrovascular disease (P = 4.6 × 10−4), GALNT16 with angina (P = 9.3 × 10−4), MBOAT7 with venous thromboembolism (P = 1.3 × 10−3), GLTPD2 with atherosclerosis (P = 5.3 × 10−4) and SPTLC3 with intracerebral haemorrhage (P = 1.0 × 10−3)." (PMID 31551469, 2019).
dementia (1 paper, 2025). Loss of intellectual abilities interfering with an individual's social and occupational functions. "Gene-drug interaction analysis identifies higher levels of GLTPD2 modifying the antidepressants associated increase in dementia risk contributing to a 73.3% risk reduction relative to the use of drugs." (PMID 40799764, 2025). "Our pharmacogenomic analysis identifies TRIM2, FBXO44, and GLTPD2 as potential genetic modifiers, whose higher expression levels attenuate the deleterious effects of N06AX antidepressants on WMH burden, with GLTPD2 also reducing dementia risk." (PMID 40799764, 2025).
GLTPD2 also shares sentences with these, for which no sentence is quoted: abortion (1 paper); atherosclerosis (1); cerebrovascular disease (1); intracerebral haemorrhage (1); venous thromboembolism (1).